CD4 (CD4 molecule)
Diseases named in the same sentence as CD4 in open-access papers (continued):
Sharing a sentence is not in itself a finding about the gene and the disease.
AIDS (continued). "Human immunodeficiency virus (HIV), the causative agent of acquired immune deficiency syndrome (AIDS), is a retrovirus that infects CD4+ cells (including T cells, NKT cells, macrophages and DCs)." (PMID 23202469, 2012). "Co-infection with SIV and BCG accelerated progression to AIDS and coincided with a severe depletion of CD4+ T cells, loss of BCG-specific T cell responses, and reactivation of the clinically latent BCG infection into a TB-like disease." (PMID 22363214, 2012). "We assessed 368 PLWHA for major depressive disorder, as well as for potentially associated factors, including AIDS-related stigma, CD4 levels, presence of opportunistic infections, and sociodemographic variables." (PMID 23209556, 2012). "Drug interaction complicates the strategies, especially during AIDS, when resurgence of viral load and associated suppression of CD4 increase the risks of AIDS-related death and TB IRIS." (PMID 23209581, 2012). "Here we show an increased risk of AIDS or death with lower time updated CD4 cell count in successfully treated patients." (PMID 22448150, 2012). "It was, therefore, suggested that the decline of Gag antibodies with progression to AIDS is due to the loss of CD4+ T cell help, while a T cell independent antibody response to Env allows persistence of Env antibodies." (PMID 22583867, 2012). "An association between CD4 count and non-AIDS related mortality has been reported, albeit of weaker magnitude compared with that for AIDS-related mortality." (PMID 22905264, 2012). "As expected, low CD4+ T-cell count at presentation associates with increased risk of AIDS defining illnesses." (PMID 22110905, 2012). "Though set point VL has been shown to be a relevant marker for disease progression, CD4+ T cell counts are traditionally used to define those individuals that have progressed to AIDS and are at a higher risk for opportunistic infections." (PMID 23209412, 2012). "In contrast, it can take 48 hours or longer to obtain more specific CD-4 counts and AIDS enzyme-linked immunosorbent assay (ELISA) serology." (PMID 23882358, 2012). "Despite the low mortality rate, the risk of a new AIDS event or death follows a CD4 cell count gradient in patients with viral suppression." (PMID 22448150, 2012). "HIV-1 causes a chronic infection in humans that is characterized by high plasma viremia, progressive loss of CD4+ T lymphocytes, and severe immunodeficiency resulting in opportunistic disease and AIDS." (PMID 23170180, 2012). "Women achieved better long-term immune response to ART, reaching CD4 level associated with lower risks of AIDS related morbidity and mortality quicker than men." (PMID 22363550, 2012). "Progression to AIDS is usually accompanied by (i) rising VL, (ii) substantial loss of CD4+ T-cells in peripheral blood, and (iii) risk for opportunistic infections and malignancies." (PMID 23202454, 2012). "Epidemiological studies suggest that HIV positive cocaine users have lower CD4+ T cell counts, increased risk of diseases progression and AIDS-related death." (PMID 23251514, 2012). "Studies in patients nor receiving cART have convincingly shown that increased levels of cellular and soluble markers of immune activation are linked to higher risk of progression to AIDS, lower CD4 counts and poorer prognosis." (PMID 22815704, 2012). "The highest rates of new AIDS-defining events or death were seen in those patients with less than 50 CD4 cells/μl blood and a higher CD4 cell count was associated with a reduced risk of a new AIDS-defining event or death." (PMID 22448150, 2012). "The central role of CD4+ T cells in protection against TB has been clearly demonstrated by the increased susceptibility to Mtb infections in HIV/AIDS patients in correlation with diminished CD4+ T cell counts." (PMID 23110186, 2012).
AIDS (continued). "Diagnostic characteristics of the WHO HIV/AIDS clinical staging guidelines at the CD4 cell count of less than 250 cells/mm3 and 350 cells/mm3 among 395 participants in JCRC Mengo, Kakira and Kasana health centres, Uganda." (PMID 21589912, 2011). "The programme consists of systematic screening of all high-risk patients (CD4 <100 cells/mm3) by AIDS clinicians using indirect ophthalmoscopy, and treatment of all patients with active retinitis by intravitreal injection of ganciclovir." (PMID 21843351, 2011). "Some risk factors demonstrated a strongest association with VTE such as like a diagnosis of AIDS, low CD4+ cell count especially in the presence of clinical AIDS, protein S deficiency, and protein C deficiency." (PMID 21869916, 2011). "Systematic screening of all high-risk patients (CD4 <100 cells/mm3) was carried out at five separate AIDS clinics throughout Myanmar." (PMID 21843351, 2011). "As our group recently reported, most HIV controllers have abnormally high levels of immune activation, which is associated with significant CD4+ T cell depletion and even AIDS despite continued control of virus replication." (PMID 21305005, 2011). "There is now growing evidence that patients with CD4 T-cell counts <500 cells/μl are at an increased risk of AIDS and non-AIDS defining illnesses, despite achieving complete viral suppression on cART." (PMID 21674057, 2011). "The AIDS patients with CD4+ T lymphocyte < 50 cells/μl had increased susceptibility to cytomegalovirus associated retinitis." (PMID 22115120, 2011). "During the chronic phase of the infection, blood CD4+ T cell count declines slowly; this loss can be partially reversed by successful antiretroviral treatment, but it is accelerated during AIDS." (PMID 21994747, 2011). "Higher T cell activation has also been independently associated with more rapid CD4+ T cell decline and clinical progression to AIDS in untreated HIV-infected individuals." (PMID 21305005, 2011). "Higher CD4+ cell counts have been linked to higher HRQoL scores in women and men, whereas the presence of AIDS has been linked to lower self-perceived physical health scores in both sexes." (PMID 21904672, 2011). "The exception was an envelope protein obtained from the cerebral spinal fluid of an infected macaque that developed severe CD4+ T cell loss and AIDS." (PMID 21284906, 2011). "CD4 T-cell recovery following cART is variable and patients who fail to achieve CD4 T-cell counts >500 cells/μl remain at risk of AIDS and non-AIDS defining illnesses." (PMID 21674057, 2011). "Some risk factors demonstrated a strongest association with VTE such as, low CD4+ cell count especially in the presence of clinical AIDS, protein S deficiency, and protein C deficiency." (PMID 21869916, 2011). "Women with advanced degrees of imunossupression (CD4 < 350 or AIDS) had a significantly higher risk of transmitting HIV to their newborns, similarly to results found in literature." (PMID 22129112, 2011). "At the time of initiation of therapy, almost half of the patients had an advanced immune deficiency (CD4 cells below 200/μl) and 20% had already suffered from an AIDS-defining condition." (PMID 22205931, 2011). "As compared to untreated disease, those who remain on a stable regimen despite the presence of drug-resistance mutations have slower rates of CD4+ T cell decline and a lower risk of progressing to AIDS and/or death." (PMID 21701594, 2011). "Presently, it is assumed that IFNα alone contributes to the progression of AIDS disease, however a decrease in CD4+T cells is also associated with a significant increase in serum levels of inflammatory cytokines including TNFα." (PMID 21994776, 2011). "Higher copy numbers of the activating KIR2DS2 were associated with greater CD4+ T cell loss and rapid progression to AIDS." (PMID 22194686, 2011).
AIDS (continued). "Among untreated individuals, the level of viremia is only partially predictive of the rate of disease progression, as defined by the rate of CD4+ T cell loss and/or by the risk of progressing to AIDS and death." (PMID 21701594, 2011). "Generally, the shift from the chronic phase to the AIDS phase is due to the balance between viral growth and immune suppression, and the remarkable decrease in CD4+ T cells causes the subsequent deficiency of the immune system, the hallmarks of AIDS." (PMID 21858176, 2011). "Human immunodeficiency virus (HIV-1), the cause of acquired immunodeficiency syndrome (AIDS), enters cells by attaching its major surface component, the envelope glycoprotein spike, to a receptor protein on the target cell called CD4." (PMID 21731494, 2011). "Shortly thereafter, serology for HIV returned positive along with a depressed CD4 cell count, and the patient was diagnosed with AIDS-associated cholangiography." (PMID 21994858, 2011). "In examination of six SIV seropositive SMs with AIDS-defining CD4+ T cell levels, variants with expanded coreceptor usage that included CXCR4 and CCR8 were identified in two mangabeys." (PMID 21284906, 2011). "A low CD4 T-cell count measured at AIDS onset was associated with significantly increased risks of HPV-associated invasive cancers, including anal cancers among men and vaginal or vulvar cancers among women." (PMID 24212964, 2011). "This pattern of CD4+ T cell changes observed in SIVagm-infected RMs is unprecedented and significantly differs from SIVsmm/mac-infected RMs that show continuous, persistent loss of mucosal CD4+ T cells during chronic infection and progression to AIDS." (PMID 21829366, 2011). "CD4 cell count is a strong predictor of the subsequent risk of AIDS or death in both untreated HIV-infected individuals and in those initiating combination antiretroviral therapy (cART)." (PMID 20186270, 2010). "There was a significant association between CD4 cell slope and the 2-y risk of AIDS events or deaths in these cART-naive patients with an adjusted hazard ratio of 0.96 (95% CI 0.94–0.98) for each 10 cells/μl per year reduction in CD4 cell decline." (PMID 20186270, 2010). "In the main trial, we found that HIV-DNA level at treatment interruption, in addition to CD4 nadir and prior AIDS event, was the only significant risk factors of reaching criteria to resume cART." (PMID 20657770, 2010). "Late presentation with low baseline CD4 T cell counts and presence of AIDS defining and/or AIDS associated symptoms is the strongest prognostic marker for early mortality in both low and high income countries." (PMID 20626905, 2010). "To further study if increased monocyte turnover can predict rapid progression to AIDS, we examined other parameters previously linked to disease progression including CD4+ T lymphocyte numbers, CD4+ T lymphocyte turnover, and plasma viral load." (PMID 20419144, 2010). "Among those who received HAART, additional risk factors for death included baseline CD4 cell count <50/μL, age ≥60 years at AIDS diagnosis, baseline hemoglobin <8 g/dL, and having 4–5 baseline signs and symptoms at treatment initiation." (PMID 21060835, 2010). "This analysis suggests that decreasing CD4+ counts are a significant risk factor for clinical deterioration because of their association with HIV-1 related illnesses (either AIDS- or non AIDS-defining illnesses)." (PMID 20353569, 2010). "HIV is a member of the lentivirus family that infects cells found in the human immune system, primarily CD4+ T cells, leading to acquired immune deficiency syndrome (AIDS)." (PMID 21042592, 2010). "Cys55 is next to Nef motif A56W57L58, a site implicated in the interaction of Nef with CD4, Nef-mediated CD4 downregulation and the onset of AIDS." (PMID 20659345, 2010).
AIDS (continued). "The overall Nef functions were vindicated in HIV-1 pathogenesis when Nef deleted HIV-1 infected patients showed delayed progression towards Acquired Immuno Deficiency Syndrome (AIDS) which had undetectable/low viral load with normal CD4 count." (PMID 21179446, 2010). "Cryptosporidium parvum is a frequent cause of diarrhea in AIDS patients, especially those with a CD4 count < 100/ul." (PMID 21029408, 2010). "Untreated HIV infection leads to a decrease in CD4+ T cell count, eventually resulting in the loss of cell-mediated immunity, an immunocompromised state and the onset of AIDS (Acquired Immunodeficiency Syndrome)." (PMID 20529270, 2010). "Increased percentage of BrdU+ monocytes correlated with AIDS more so than CD4+ T lymphocyte loss or viral load." (PMID 20419144, 2010). "CD4 cell count is a strong predictor of the subsequent risk of AIDS or death in HIV-infected patients initiating combination antiretroviral therapy (cART)." (PMID 20186270, 2010). "In an analysis adjusted for established risk factors, the hazard ratio for AIDS or death was 1.01 (95% confidence interval 0.97–1.04) for each 10 cells/μl per year reduction in pre-cART CD4 cell decline." (PMID 20186270, 2010). "Thereupon, a reduction in CD4 T cells to below 200 cells/uL makes the host highly susceptible to opportunistic infections and increases overall AIDS related morbidity and mortality." (PMID 20626905, 2010). "Each of the patients had X4 strains, which are known to be associated with a higher rate of decline of CD4+ T-cells, and therefore, a more rapid progression to AIDS." (PMID 19531207, 2009). "We showed that co-infected patients progress with higher levels of CD4+ T cells expressing activation markers and a massive loss of naïve cells, thus suggesting that co-infected patients progress faster to AIDS." (PMID 20028500, 2009). "The CD4 slope which represents changes in numbers of CD4 T-cells over time strongly predicts HIV disease progression; an annual CD4 depletion of 10 additional cells/μl has been associated with a 2% increased likelihood of developing AIDS." (PMID 19142234, 2009). "HIV-mediated CD4 depletion is the hallmark of AIDS and is the most reliable predictor of disease progression." (PMID 19409100, 2009). "Pulmonary hypertension, associated with HIV/AIDS, differs from idiopathic/ primary pulmonary hypertension in terms of rapidity of progression, is unrelated to CD4 count and is associated with a worse prognosis compared to non- AIDS patients." (PMID 20436855, 2009). "Progressive CD4+ T cell decline in human immunodeficiency virus (HIV) infection, the slow but persistent loss of both naïve and memory CD4+ T cells, is an important marker of progression to AIDS." (PMID 19360097, 2009). "The decline of CD4+ T cells in pathogenic models of AIDS infected with a CCR5-tropic virus is mainly due to a loss of memory CD4+ T cells." (PMID 20011508, 2009). "Infection by the human immunodeficiency virus (HIV) causes severe depletion of the CD4 T cell population, which eventually leads to acquired immunodeficiency syndrome (AIDS)." (PMID 20041213, 2009). "The identification of the CD4 receptor as the primary receptor for HIV seemed initially to explain the loss of CD4+ T cell lymphocytes in AIDS." (PMID 19360097, 2009). "Studies of relative risks of AIDS and/or death associated with higher RNA viral load or lower CD4 cell count, in populations of HIV-1 infected adults." (PMID 19536329, 2009). "Simian AIDS pathology includes high viral load in the peripheral circulation, hematopoietic abnormalities and loss of CD4+ lymphocytes in the peripheral blood, and in the gut-associated lymphoid tissue." (PMID 19888329, 2009). "Chronic SIV-infection of macaques provides a relevant and useful model to explore the mechanisms for progressive CD4+ T cell loss in AIDS pathogenesis." (PMID 19360097, 2009).
AIDS (continued). "Regarding immunological response, a higher CD4 cell count while receiving antiretroviral treatment gained, a lower risk for AIDS-related events was associated." (PMID 20030841, 2009). "The R5-to-X4 switch is strongly associated with a poor clinical prognosis for the patient: it occurs with a steep loss in CD4+ T cell counts and accelerated AIDS onset." (PMID 19680436, 2009). "It have been proved that the emergence of SI viruses is associated with an accelerated decrease in CD4 T cell count, rapid disease progression and the establishment of AIDS." (PMID 19922621, 2009). "This suggests that the induction of anti-CD4+ T cell antibodies is one of the important factors causing a slow depletion of CD4+ T cells over the long asymptomatic period leading to AIDS." (PMID 19360097, 2009). "Several studies have shown an association between anti-CD4+ T cell antibodies with CD4 T+ cell depletion and disease progression, suggesting the potential contribution to AIDS pathogenesis." (PMID 19360097, 2009). "In advanced HIV infection where the individuals experienced virologic failure to all three ARV drug classes, baseline CD4 count was found to be a strong predictor of short-term risk of AIDS and death." (PMID 18454861, 2008). "Comparing clinical event rates between ART-naives and cART-treated follow-up within CD4 cell strata above 200 cells/mm3, the risk of AIDS before ART initiation is higher than the risk following cART initiation." (PMID 18923700, 2008). "This decision relies heavily on assessing AIDS risk based on the CD4+ T cell count and plasma viral load." (PMID 18776933, 2008). "In a previous study, 1604G was observed to be associated with a more rapid CD4+ T-cell decline in African Americans and a trend towards more rapid progression to AIDS was observed in European Americans." (PMID 19092998, 2008). "The role of the CD8 cell-surface molecule in HIV-1 infection cannot be discounted as recent evidence has shown that CD4-independent HIV-1 variants exist in AIDS patients and these viruses preferentially infect CD8+ T-cells using CD8 as a receptor." (PMID 18923697, 2008). "HIV-1-infected subjects are typically started on highly active antiretroviral therapy (HAART) when their CD4+ T cell count reaches a threshold below which their risk for developing AIDS increases significantly." (PMID 18776933, 2008). "This is true for our study in which an AIDS-associated Nef was reduced in its ability to downmodulate CD4 and enhanced in its ability to downmodulate MHC I and is also true for other studies where the reverse was found." (PMID 18510766, 2008). "There is substantial data demonstrating that polymorphisms in CCR5 are associated with variable susceptibility to HIV, AIDS progression rates, and CD4+ T cell count recovery during HAART." (PMID 18776933, 2008). "There is limited data on the frequency of suboptimal CD4 reconstitution despite viral suppression (SO-CD4) in sub-Saharan Africa (SSA) where most patients initiate ART at advanced stages of HIV/AIDS amidst a high background risk acute infections." (PMID 18957083, 2008). "Human imunodeficiency virus (HIV) is the causative agent of acquired immunodeficiency syndrome (AIDS), which triggers the decline of CD4+ T cells and leads to immune system dysfunction." (PMID 18261236, 2008). "C98's CD4+ T cells declined to nearly 200 cells/ml, and received anti-viral therapy for 16 months before dying of non-AIDS causes." (PMID 18808677, 2008). "CCR5-using (R5) viruses are mainly transmitted, while CXCR4-using (X4) variants can be isolated from up to 50% of AIDS patients in subtype B infections and correlate with a more rapid loss of CD4+ T-cells and faster disease progression." (PMID 18205925, 2008). "Cox proportional hazards modeling demonstrated that Group C was associated with the fastest rate of progression to AIDS, whereas group B (subjects with a CD4 cell count of <453453 cells/mm3) was associated the slowest rate of disease progression." (PMID 18776933, 2008).